CCL2 (C-C motif chemokine ligand 2)
Diseases named in the same sentence as CCL2 in open-access papers (continued):
Sharing a sentence is not in itself a finding about the gene and the disease.
atherosclerosis (continued). "The literature supports the importance of the CCL2 (MCP-1)—CCR2 axis in human atherosclerosis, highlighting its relevance and therapeutic potential." (PMID 37175617, 2023). "C-C motif chemokine ligand 2 (CCL2/MCP1) is a monocyte-specific surface marker that accelerates atherosclerosis and shows an increased expression in atherosclerotic lesions." (PMID 37081240, 2023). "This suggests that natto inhibits atherosclerosis through suppression of intestinal inflammation and reduced CCL2 expression in macrophages." (PMID 38110459, 2023). "CCL2 seems to be involved in the recruitment of monocytes into the arterial wall during the disease process of human atherosclerosis." (PMID 37526658, 2023). "The Ccl2-induced migration of monocytes to the vessel wall is an essential activity contributing to the development of atherosclerosis." (PMID 37888673, 2023). "CCl2 has been demonstrated to influence atherosclerosis progression through its effects on monocyte trafficking and lipid deposition in atherosclerotic plaques using different mouse models." (PMID 37046189, 2023). "The Pull‐down experiment further verified that the mechanism of lncRNA‐CCL2 was to regulate the expression of CCL2 and promote atherosclerosis through the interaction with RNA‐binding proteins." (PMID 36872292, 2023). "CCL2, a monocyte-specific surface marker that induces local inflammation and accelerates atherosclerosis, showed an upregulation on mRNA and protein levels for only 3R4F but not consistently for NGP treatment." (PMID 37081240, 2023). "MCP-1/CCL2 was found in the synovium of patients with rheumatoid arthritis (RA), gout, traumatic arthritis, atherosclerosis, multiple sclerosis and various cancers." (PMID 36768186, 2023). "These genes are involved in cholesterol metabolism (Abca1, Abcg8, Abcg5, Lpl, Cyp7a1, and Pltp), lipid and atherosclerosis (Abca1, Il1b, Ccl2, and Abcg1), bile secretion (Abcg8, Abcg5, and Cyp7a1), and IL-17 signaling pathway (Ccl7, Il1b, and Ccl2)." (PMID 37301941, 2023). "Ox-LDL or disturbed flow induce monocyte chemoattractant protein-1 (MCP-1) expression on the vascular wall, which mediates monocyte recruitment and atherosclerosis through the interaction between CCL2 on MCP-1 and CCR2 on monocytes." (PMID 37371110, 2023). "Findings suggest that natto intake therapeutically affects atherosclerosis by modulating gut microbiota composition and regulating the expression of pro-atherosclerotic cytokines and chemokines, such as CCL2." (PMID 38110459, 2023). "Due to its important role in the inflammatory cascade, CCL2 has become a therapeutic target for various inflammatory diseases such as insulin resistance, atherosclerosis, ischemic injury, and cancer." (PMID 36872292, 2023). "As a chemokine, CCL2 expression was significantly elevated in diseased arteries and correlated significantly with the predictive value of atherosclerosis." (PMID 37476576, 2023). "Increased CCL2 production has also been described in several pathological conditions, mainly autoimmune disorders such as diabetes, atherosclerosis, rheumatoid arthritis, multiple sclerosis and in a wide variety of solid cancers." (PMID 38130717, 2023). "CCR2 is highly expressed by monocytes and binds to CCL2 which is primarily secreted by monocytes, macrophages and dendritic cells, supporting a primary role for monocyte/macrophage activation in atherosclerosis." (PMID 37927302, 2023). "We found that the combined inhibition of TNFα, CXCL2 and CCL2 in recipients with aged fat transplants substantially reduced the degree of atherosclerosis at the carotid artery, aortic root and BCA." (PMID 36683460, 2023).
atherosclerosis (continued). "In the early stage of atherosclerosis, activated endothelial cells secrete monocyte chemoattractant protein-1/C-C chemokine ligand 2 (MCP-1/CCL2), and its receptor C-C Motif Chemokine Receptor 2 (CCR2) is highly expressed on the surface of monocytes." (PMID 36483980, 2022). "We also observed the downregulation of genes encoding monocyte chemoattractant protein-1 (MCP-1 or CCL2) and its receptor CCR2 that are involved in monocyte/macrophage migration and are found upregulated in atherosclerosis." (PMID 35694160, 2022). "In our previous study, we demonstrated that MK2206 suppressed atherosclerosis by inhibiting inflammation, and CCL2 was reduced in this mouse model after the treatment of MK2206." (PMID 35990936, 2022). "Blocking CCL2/MCP-1 and its receptor can inhibit monocyte adhesion in the vessel wall, attenuating artery intimal hyperplasia and atherosclerosis." (PMID 35966541, 2022). "CCL2-induced migration of monocytes to the vessel wall is a key activity contributing to the development of atherosclerosis." (PMID 36110847, 2022). "We decided to point our attention to BAF modulation of CCL2, as this chemokine has been already linked to BBB damage in several inflammatory and infectious disorders, such as atherosclerosis and MS, and also to S1P signaling." (PMID 34599741, 2022). "CCL2 acts as a trigger for monocyte trafficking across the endothelium during the onset and development of atherosclerosis." (PMID 36703734, 2022). "At early stages of atherosclerosis, the release of CCL2 and T-cell chemoattractants recruits monocytes and lymphocytes into the inner arterial wall, where monocytes are differentiated into macrophage foam cells under the influence of M-CSF." (PMID 35328769, 2022). "We found that nonatherosclerotic suPARTg aortas secreted significantly higher levels of C-C motif chemokine ligand 2 (CCL2), one of the primary monocyte chemoattractants implicated in atherosclerosis, compared with WT aortas." (PMID 36194491, 2022). "Results from our study showed that expression of CCR2 and CCL2 on the mRNA level was shown only in atherosclerotic patients with non-fatal ACS, thus confirming the association of PMAs formation with atherosclerosis and ACS." (PMID 35563407, 2022). "Overall, as CCL2 has been shown to be overexpressed in atherosclerotic lesions it is likely that it plays a prominent role in vascular remodeling of VSMCs in atherosclerosis." (PMID 35600479, 2022). "The CCL2/CCR2 axis regulates the inflammatory recruitment of classical monocytes in atherosclerosis, as well as in the infarcted heart." (PMID 35743792, 2022). "Cardiovascular studies have demonstrated higher expression of CCL2/CCR2 increased the risk for higher platelet response, atherosclerosis, and thrombus formation." (PMID 35749425, 2022). "Prior to induction of atherosclerosis, aortas of suPARTg mice excreted higher levels of CCL2 and had higher monocyte counts compared with WT aortas." (PMID 36194491, 2022). "Lipid peroxides, interleukins, angiotensin II, homocysteine, activated platelets, and shear stress, among other mediators of atherosclerosis, induce CCL2 synthesis and secretion by endothelial cells and smooth muscle cells." (PMID 34356595, 2021). "Targeting CCL2 signaling has attracted a lot of attention for potential clinical applications in the treatment of various types of cancer, atherosclerosis, multiple sclerosis, and type 2 diabetes." (PMID 33540898, 2021). "Inhibition of the isoenzyme of glutaminyl cyclase that is responsible for cyclization of glutamine into pyroglutamic acid, coincided with reduction of CCL2-driven monocyte recruitment in vivo with beneficial effects on atherosclerosis progression." (PMID 33777041, 2021). "Deficiency in CD36 has been shown to be reduce proinflammatory signaling, cell recruitment, Ccl2 and Vcam1 levels in models of ischemic stroke and atherosclerosis." (PMID 34496918, 2021).
atherosclerosis (continued). "Considering the reduced CCL2 and necrotic core level by IF, it will be worthy investigating if autophagy involved in IF-reduced atherosclerosis in the future." (PMID 34658858, 2021). "Previously, PC‐mAb was shown to reduce CCL2 levels produced by human monocytes stimulated with oxLDL in vitro and regarding accelerated atherosclerosis local expression of CCL2 in the vessel wall was inhibited." (PMID 34190404, 2021). "C–C motif chemokine 2 (CCL2) also named Monocyte chemotactic protein 1(MCP-1) is one of the chemotactic factors produced by damaged endothelial cells during the development of atherosclerosis." (PMID 34627325, 2021). "In the initiation and progression of atherosclerosis, CCL2 functions as a direction cues trafficking of monocytes across the endothelium." (PMID 34345249, 2021). "A considerable body of evidence indicates that activation of the CCL2/CCR2 axis is important in the pathogenesis of atherosclerosis." (PMID 34356595, 2021). "When crossed with low density lipoprotein (LDL) receptor-deficient mice, CCL2 has been shown to reduce atherosclerosis upon high-cholesterol diets, suggesting an important role of CCL2 in the initiation of atherosclerosis." (PMID 33540898, 2021). "SARS-CoV-2 interactome strongly connects with the complete ACE2 network through INS, CDK4 (Cyclin-Dependent Kinase 4), CCL2, and ALB (Albumin), all of them associated with atherosclerosis processes." (PMID 33233425, 2020). "Conversely, overexpression of CCL2 by the myeloid compartment was sufficient to exacerbate atherosclerosis progression." (PMID 33374145, 2020). "In the Apoe−/− mouse model of atherosclerosis, influenza virus infection increases the levels of IL-1β, IL-6, G-CSF, GM-CSF, CCL2, CCL3, and CCL5 in the serum." (PMID 33193350, 2020). "7ND was successfully tested in a number of preclinical and CCL2-related animal models, such as atherosclerosis and restenosis or renal fibrosis." (PMID 32934311, 2020). "Primary proinflammatory cytokines produced by macrophages during atherosclerosis initiation and development are IL-1β, IL-6, TNFα, and CCL2." (PMID 33374145, 2020). "Consistent with the lower foam cell and macrophage positive area, we found that Apoe–/–/Treml4–/– mice had lower levels of circulating Ccl2 while other cytokines relevant to atherosclerosis remained unchanged." (PMID 32292401, 2020). "The linear random effect model allowed us to pinpoint other possible effects of DNT5 (adipose tissue expression of Il6, Il1β, Ccl2, atherosclerosis in the artic conduit, hepatic expression of Srebp1c and Acaca)." (PMID 30692584, 2019). "When conjugated with gadolinium or europium cryptates, CCTV enabled targeted imaging (via magnetic resonance imaging and time-resolved fluorescence) of atherosclerosis, a chronic inflammatory condition in which the CCL2/CCR2 axis is highly dysfunctional." (PMID 31723548, 2019). "CCL2 or MCP-1 is a marker of the persistent infiltration of low-grade inflammatory monocytes contributing to aggravated atherosclerosis." (PMID 31821324, 2019). "In fact, in the pre-clinical setting, blockade of receptors for CCL2 or preventing immune cells from being activated reduces BP, in addition to slowing the development of atherosclerosis and vascular hypertrophy." (PMID 31427987, 2019). "CCL2 is best known for the chemotactic properties of monocytes and involvement in atherosclerosis development." (PMID 31396527, 2019). "Further, the induction of COX-2 is required for CCL2 expression by monocytes during the progression of atherosclerosis." (PMID 30974834, 2019). "Numerous studies have demonstrated the importance of the CCR2/CCL2 (MCP-1), CX3CR1/CX3CL1 (fractalkine), CXCR2/CXCL1, and CCR5/CCL2/CCL5 interactions in the progression of experimental atherosclerosis." (PMID 31195722, 2019). "Accordingly, MCP-1/CCL2 is considered as a potential intervention target in atherosclerosis and diabetes with insulin resistance." (PMID 31109070, 2019).
atherosclerosis (continued). "RANTES mainly derives from activated platelets and its role seems to be crucial in the initiation of atherosclerosis plaque formation, while CCL2 recruits monocytes which contribute to the progression of atherosclerotic lesion." (PMID 31396527, 2019). "This suggests that Ly6Chigh monocyte recruitment, mediated by CCR2 and CCL2, to the plaque is essential for atherosclerosis progression." (PMID 29868610, 2018). "Other works have pointed the participation of CCL2 in the pathogenesis of several inflammatory disorders such as atherosclerosis and autoimmune diseases." (PMID 30143000, 2018). "The chemokine CCL2 plays an important role in the recruitment of monocytes into site of inflammation and thereby triggers several diseases including atherosclerosis, type 2 diabetes and rheumatoid arthritis." (PMID 30237533, 2018). "The ‘M3’ chemokine binding protein inactivates key chemokines involved in atherosclerosis (e.g. CCL2, CCL5 and CX3CL1)." (PMID 28282403, 2017). "In vivo studies using mice susceptible to atherosclerosis, with genetic deficient in MCP-1 (CCL2) or its receptor, CCR2, have demonstrated significant protection against lesion formation, possibly by a decreased subendothelial monocyte accumulation." (PMID 28969682, 2017). "CC Chemokine Receptor 2 (CCR2) and its endogenous ligand CCL2 are involved in a number of diseases, including atherosclerosis." (PMID 28246398, 2017). "The knockout and transgenic studies provide convincing proof that individual chemokine-chemokine receptor signalling pathways are important in atherosclerosis, particularly the CCL2/CCR2, CCL5/CCR5 and CX3CL1/CX3CR1 pathways." (PMID 28282403, 2017). "In order to study the functional effect of irradiation on inflammatory processes in ECs, we focused on 3 pro-inflammatory cytokines known to be involved in atherosclerosis: IL-6, IL-8, and CCL2." (PMID 28993729, 2017). "CCL2 is a member of the CC chemokine family that is highly involved in the initiation and progression of atherosclerosis (8, –, 10)." (PMID 27458015, 2016). "The capacity of RCT was shown to be impaired during low degree inflammation in the progression of atherosclerosis, but little is known regarding how CCL2 influences the early step of RCT together with HDL internalization and cholesterol efflux to HDL in ECs." (PMID 27458015, 2016). "Although the phenotypes of CCL2- and CCR2-deficient mice are concordant in models of inflammatory disease such as atherosclerosis or experimental allergic encephalitis, they differ in other settings." (PMID 27820834, 2016). "A number of studies have demonstrated that genetic deletion of CCL2 or CCR2 slowed the disease course in animal models of atherosclerosis." (PMID 27458015, 2016). "Accordingly, local overexpression of CCL2 at the vessel wall in combination with hyperlipidemia accelerates atherosclerosis by promoting the infiltration of macrophages into atherosclerotic lesions." (PMID 26001902, 2015). "TNF-α and CCL2 are key mediators in chronic inflammatory processes like arthritis and atherosclerosis and the plants were selected based on their traditional use to treat these diseases or other inflammatory conditions." (PMID 25878716, 2015). "The present study shows (by immunostaining) that paraoxonases, CCL2 and several CCL2 receptors are increased in peripheral arteries with indications of atherosclerosis." (PMID 25993297, 2015). "Stimuli such as hyperlipidemia, disturbed flow or angiotensin II induce the expression of CCL2 during atherosclerosis." (PMID 26001902, 2015). "The pro-inflammatory chemokine, CCL-2 (monocyte chemoattractant protein-1, MCP-1), plays a fundamental role in monocyte recruitment and has been implicated as a contributing factor to atherosclerosis." (PMID 26305254, 2015). "Atherosclerosis is an inflammatory disease, and the consensus is that CCL2 is involved in its pathogenesis." (PMID 25993297, 2015).
atherosclerosis (continued). "Tumor necrosis factor- (TNF-) α and chemokine (C-C motif) ligand 2 (CCL2) are key inflammatory mediators in diseases like rheumatoid arthritis and atherosclerosis, respectively; nevertheless, only a few extracts have been assayed against these targets." (PMID 25878716, 2015). "Evidence for an essential role of CCL2 in macrophage activation in disease models such as atherosclerosis and asthma, together with the observation that inflammatory stimuli induce its expression, has led to consideration of CCL2 as an inflammatory chemokine." (PMID 23866683, 2013). "Monocyte chemoattractant protein-1 (MCP-1), a CC chemokine (CCL2), has been demonstrated to play important roles in atherosclerosis and becoming an important therapeutic target for atherosclerosis." (PMID 22428064, 2012). "Among a number of chemokines implicated in atherosclerosis, MCP-1 (i.e., CCL2) is the key chemokine responsible for accumulation of inflammatory cells in atherosclerotic lesions after interaction with its receptor CCR2." (PMID 22428064, 2012). "Several chemokines including CXCL1/growth-related oncogene (GRO)-α, CXCL8/interleukin (IL)-8 and CCL2/monocyte chemoattractant protein (MCP)-1 are important in the pathogenesis of atherosclerosis and can be influenced by statin-treatment." (PMID 22815786, 2012). "Ccl-2 is well known for its involvement in monocyte adhesion during the early development of atherosclerosis." (PMID 20864429, 2011). "The reason for our intention was that the chemokine MCP-1/CCL2 belongs to key inflammatory CC chemokines playing central role in atherosclerosis and cardiovascular disease development—disease states guided with chronic low-grade inflammation." (PMID 19639050, 2009). "Chemokine IL-8/CXCL8 is known to play an important role in the migration of monocytes into the subendothelial space in the early phase of atherosclerosis, and along with MCP-1/CCL2, plays an important role in the pathogenesis of atherosclerosis." (PMID 20107546, 2009). "Taken together, the present study demonstrates a diminshed release of IL-6 and CCL2 from LPS activated T1D monocytes indicating an impaired primary immune response that subsequently promotes atherosclerosis in these patients." (PMID 16566827, 2006). "CC-chemokine ligand 2 (CCL2) is involved in the pathogenesis of several diseases associated with monocyte/macrophage recruitment, such as HIV-associated neurocognitive disorder (HAND), tuberculosis, and atherosclerosis." (PMID 37961304, 2025). "Conversely, overexpression of Ccl2 accelerated atherosclerosis in Apoe−/− mice." (PMID 40119478, 2025). "Unsupervised DEGs analysis of SMCs revealed increased expression in Abcb8ECKO of TGF-β-pathway genes such as Tgfb1, Tgfb2, Tgfb3, Mmp2 and Col1a1, inflammatory genes such as Ccl2 (encoding for MCP1) and Csf1 as well as atherosclerosis-associated genes including Egr1, Sqstm1, Irf1, Sox4 and Xylt1." (PMID 41252867, 2025). "Preclinical data suggest that pharmacological targeting of CCL2 or its receptor CCR2 might lower atherosclerosis burden in experimental models." (PMID 40119478, 2025). "Additionally, studies investigating the role of the LTB4/BLT1 axis in atherosclerosis have demonstrated that LTB4 can also stimulate the production of monocyte chemoattractant protein-1 (MCP-1/CCL2)." (PMID 39769189, 2024). "Apparently, these events constitute the initial stage of endothelial dysfunction and atherogenesis in SLE.20 21 Furthermore, activation of ECs triggers proinflammatory cytokines, for example, CCL2, which play a direct role in accelerated atherosclerosis in SLE." (PMID 39242108, 2024). "Moreover, lncRNA CCL2 is highlighted for its contribution to human atherosclerosis by upregulating CCL2 mRNA levels in endothelial cells, pointing to a complex network of lncRNA-mediated regulation in the vascular system." (PMID 38791250, 2024).